SUMO4 (small ubiquitin like modifier 4)
Description:
Ubiquitin-like protein which can be covalently attached to target lysines as a monomer. Does not seem to be involved in protein degradation and may modulate protein subcellular localization, stability or activity. Upon oxidative stress, conjugates to various anti-oxidant enzymes, chaperones, and stress defense proteins. May also conjugate to NFKBIA, TFAP2A and FOS, negatively regulating their transcriptional activity, and to NR3C1, positively regulating its transcriptional activity. Covalent attachment to its substrates requires prior activation by the E1 complex SAE1-SAE2 and linkage to the E2 enzyme UBE2I.
Synonyms: SUMO-4; SMT3H4; dJ281H8.4; IDDM5
Tractability: PROTAC: ubiquitination databases record sites on it.
Gene: Protein-coding gene on chromosome 6 (149,400,262 to 149,401,278, forward strand). Ensembl gene ENSG00000177688.
Subcellular location (Human Protein Atlas): Nuclear bodies; Nucleoplasm; Calyx; Connecting piece; Flagellar centriole
Gene Ontology:
Molecular function: ubiquitin-like protein ligase binding
Biological process: cellular response to oxidative stress; negative regulation of DNA binding; negative regulation of DNA-templated transcription; positive regulation of DNA binding; protein sumoylation; regulation of canonical NF-kappaB signal transduction; regulation of protein localization to nucleus
Cellular component: nuclear body; nucleoplasm; SUMO ligase complex
Genetic constraint (gnomAD): Loss-of-function variants: 3 observed, 4.35 expected, observed/expected ratio (o/e) 0.69, 90% interval 0.31 to 1.64. That is too few expected variants to judge how well the gene tolerates losing a copy. Missense variants: 57 observed, 52.08 expected, observed/expected ratio (o/e) 1.09, 90% interval 0.88 to 1.36. Synonymous variants: 16 observed, 18.44 expected, observed/expected ratio (o/e) 0.87, 90% interval 0.59 to 1.32.
Homologues: Orthologues: Drosophila melanogaster Sumo (58% identical). Paralogues in human: SUMO2 (85% identical), SUMO3 (82% identical), NFATC2IP (31% identical).
Diseases named in the same sentence as SUMO4 in open-access papers:
SUMO4 is named in the same sentence as 29 diseases in open-access papers, as found by Europe PMC text mining. Sharing a sentence is not in itself a finding about the gene and the disease. The quoted sentences say what the papers report.
type 1 diabetes (12 papers, 2008 to 2022). "SUMO4 variants have previously been associated with human disease in that the SUMO4 Met55Val variant was implicated in the susceptibility to type I diabetes mellitus." (PMID 35503374, 2022). "Supporting an even broader role of SUMO isoforms in response to stress, polymorphism in the SUMO4 gene was linked to type 1 diabetes mellitus and increased SUMOylation by SUMO4 was detected in pre-eclamptic placentas." (PMID 32670048, 2020). "Several studies have demonstrated a tight link between SUMO-4 polymorphism and susceptibility to type-I diabetes." (PMID 20396415, 2010). "The observation based large controls-cohort studies yields that the presence of SUMO4 GG increased further the relative risk conferred by HLA-DR3/DR4 to type 1 diabetes, whereas SUMO4 AA decreased the risk." (PMID 20142874, 2009). "SUMO4 gene was suggested as a general autoimmunity locus in the Asian population, associations with type 1 diabetes, GD and RA have been reported." (PMID 19284637, 2009). "Genetic heterogeneity across populations had previously been reported in GD and other polygenic autoimmune diseases, such as in the case of SUMO4 gene association with type 1 diabetes, GD, or rheumatoid arthritis (RA)." (PMID 19284637, 2009). "Recently, certain SUMO4 polymorphisms have been shown to be clearly associated with type 1 diabetes in multiple Asian populations as well as with other autoimmune diseases, despite controversial observations in Caucasians." (PMID 19122825, 2008). "SUMO4 was initially shown to be associated with the pathogenesis of type 1 diabetes, but it was later reported that SUMO4 was ineffective in covalent coupling with the substrate due to the presence of proline-90 amino acid residues that prevent maturation of SUMO4." (PMID 34638970, 2021). "Overexpression of SUMO4 also contributes to enhancing the sumoylation of IκBα and regulating NF-κB activation under external stimulus stimulation, which is considered to be strongly associated with type 1 diabetes." (PMID 29038616, 2017). "Interestingly, a previous study reported that M55V substitution in the SUMO4 gene (163A→G) was strongly associated with type 1 diabetes." (PMID 24971350, 2014). "Small ubiquitin-like modifier 4 (SUMO4), a newly discovered molecule located in insulin-dependent diabetes mellitus 5 (IDDM5), has been shown to suppress the transcription of NF-κB." (PMID 29163370, 2017). "The novel polymorphism M55V, causing an amino acid change in the evolutionarily conserved met55 residue has been shown to activate the nuclear factor kappaB (NF-kappaB), hence the suspected role of SUMO4 in the pathogenicity of type 1 diabetes." (PMID 20142874, 2009). "Studies in IDDM 5 have lead to the discovery of a novel polymorphism 163 Alanine (A)->Glycine (G), of SUMO4 gene, associated with risk to type 1 diabetes in Asians, but not in Caucasians." (PMID 20142874, 2009). "Wang and colleagues have recently reviewed the correlation between SUMO-4 polymorphism and type-I diabetes, and they provided some insights to explain the discrepancy noted among different populations and the mechanisms through which SUMO4 contributes to the pathogenesis of type-I diabetes." (PMID 20396415, 2010).
diabetes (7 papers, 2009 to 2023). "SUMO4 gene rs237025 polymorphism is related to an increased risk of diabetes, therefore, it is considered a target for the gene polymorphism research of MetS." (PMID 34956330, 2021). "Currently, though SUMO4 polymorphism is associated with the susceptibility of type 1 and type 2 diabetes mellitus, the biological role of SUMO4 remains poorly understood." (PMID 24232453, 2013). "Many studies suggest that the small ubiquitin-like modifier 4 (SUMO4) M55V gene polymorphism (rs237025) may be associated with an increased risk of type 2 diabetes mellitus (T2DM)." (PMID 29163370, 2017). "Summary of meta-analysis of association between small ubiquitin-like modifier 4 (SUMO4) gene M55V polymorphism and type 2 diabetes mellitus (T2DM)." (PMID 29163370, 2017). "Sub-network from obesity and diabetes datasets indicate the significant roles of SUMO4, GAPDH and EGFR interactions in insulin signalling diabetes progression." (PMID 19997558, 2009). "Nonetheless, genetic studies have linked SUMO4 to both type 1 and 2 diabetes, suggesting a possible role for non-conjugated SUMO4." (PMID 38201212, 2023). "Other studies have suggested the susceptibility loci for T2DM may lie in the area on Chromosome 6 that SUMO4 is located, indicating a common genetic basis for both types of diabetes." (PMID 29163370, 2017). "(b) The second network demonstrates novel interactions between GAPDH and inflammatory and proliferation candidate genes i.e., SUMO4 and EGFR indicating a new link between obesity and diabetes." (PMID 19997558, 2009).
rheumatoid arthritis (5 papers, 2007 to 2021). A chronic, systemic autoimmune disorder characterized by inflammation in the synovial membranes and articular surfaces. "The most consistent pairwise effect on rheumatoid arthritis was found between two markers within MAP3K7IP2/SUMO4 on 6q25.1, although LR and RFs assigned different significance levels." (PMID 18466554, 2007). "Other genes (HAVCRI, CTLA4, SUMO4, MAP3K7IP2, PAID4, chromosome 5 locus, MIF) may also contribute to the development of rheumatoid arthritis directly or within the context of smoking." (PMID 18466513, 2007).
autoimmune disease (4 papers, 2008 to 2022). A disorder resulting from loss of function or tissue destruction of an organ or multiple organs, arising from humoral or cellular immune responses of the individual to their own tissue constituents. "In addition, a previous study reported that small ubiquitin-like modifier 4 (SUMO4) is a common autoimmune disease susceptibility gene in the Japanese population." (PMID 36076300, 2022). "Overlapping of some gene locations of different autoimmune diseases has been known and supports common pathogenic gene variants (PTPN 22, Csk, PAG, PSTPIP1, PDCD1, SLC9A3R1, CARD15, and SUMO4) transcript within these diseases." (PMID 26339139, 2015). "SUMO4 has been shown to be involved in the regulation of NF-кB, an important transcription factor in autoimmune diseases." (PMID 19122825, 2008).
Behçet's disease (3 papers, 2008 to 2012). "In a previous study, we also identified a polymorphism in a ubiquitin-related gene, SUMO4, that was associated with the susceptibility to Behçet's disease in a Chinese Han population." (PMID 22455605, 2012). "Our previous results showed an association of SUMO4 C+438T polymorphism with Behcet’s disease, another common uveitis entity observed in China." (PMID 19122825, 2008). "Interestingly, a polymorphism in a third ubiquitin-related gene, SUMO4 (small ubiquitin-like modifier 4), was associated with the risk to develop Behçet's disease in Chinese patients." (PMID 19442274, 2009).
diabetic nephropathy (3 papers, 2009 to 2019). "Studying the association of 163A/G polymorphism of SUMO4 showed a positive significant association between AA carriers and diabetic nephropathy (P < 0.05)." (PMID 26587547, 2015). "The variants of SUMO4 have been reported to be associated with T2D and diabetic nephropathy via the induction of NF-kB pathway." (PMID 19997558, 2009). "The following genes had significant association with diabetic nephropathy: eNOS, AT2R, SUMO4, IL-10, VEGF, MTHFR, ACE, and VDR." (PMID 26587547, 2015).
Insulin resistance (3 papers, 2009 to 2022). Increased resistance towards insulin, that is, diminished effectiveness of insulin in reducing blood glucose levels. "Therefore, the nonsynonymous mutation of SUMO4 may lead to an elevated expression of NF-κB, which causes insulin resistance and T2D." (PMID 34956330, 2021). "The interaction between the glycolytic protein GAPDH and the inflammatory protein small ubiquitin-like modifier 4 has been shown to induce insulin resistance in diabetic and obese individuals." (PMID 36187097, 2022). "The interaction between the glycolytic protein GAPDH and inflammatory SUMO4 suggests a potential role in the development of insulin resistance." (PMID 19997558, 2009).
type 2 diabetes mellitus (3 papers, 2013 to 2024). A type of diabetes mellitus that is characterized by insulin resistance or desensitization and increased blood glucose levels. "A recent meta-analysis has confirmed that the SUMO4 (M55V) variant is associated with both type 1 and type 2 diabetes in Asian and European populations." (PMID 39431155, 2024). "Genetic studies have linked SUMO4 to both type 1 and type 2 diabetes, suggesting that the unbound form of SUMO4 may play a role, although this association remains controversial." (PMID 39431155, 2024).
amyotrophic lateral sclerosis (1 paper, 2022). Amyotrophic lateral sclerosis (ALS) is a neurodegenerative disease characterized by progressive muscular paralysis reflecting degeneration of motor neurons in the primary motor cortex, corticospinal tracts, brainstem and spinal cord. "Recent evidence points toward a role of the small ubiquitin-like modifier (SUMO) system, including SUMO4, in protecting from stress insults and neurodegeneration, such as the progressive motor neuron disease amyotrophic lateral sclerosis (ALS), e.g., by regulating stress granule (SG) dynamics." (PMID 35503374, 2022).
Hypertension (1 paper, 2017). The presence of chronic increased pressure in the systemic arterial system. "Many factors can influence plasma concentrations of SUMO4, such as SUMO4 rs237024 and rs600739 polymorphisms, diet, smoking, and hypertension." (PMID 29163370, 2017).
Obesity (1 paper, 2009). Accumulation of substantial excess body fat. "From the information gathered regarding their individual functions, we propose that under conditions of stress and obesity, the interactions between SUMO4 and GAPDH play a role in regulating insulin and EGFR signalling to increase vascular complications in diabetic subjects." (PMID 19997558, 2009).
trauma (1 paper, 2022). "Pertinent stress factors, i.e., head trauma or cancer (treated by radiochemotherapy), were significantly more frequent in SUMO4 variant carrier versus non-carrier ALS patients." (PMID 35503374, 2022).
VKH syndrome (1 paper, 2008). "In this study, we examined the association of SUMO4 polymorphisms with VKH syndrome in the Chinese Han population." (PMID 19122825, 2008). "SUMO4 polymorphisms could also be involved in the pathogenesis of VKH syndrome, and this hypothesis was therefore the subject of the study presented here." (PMID 19122825, 2008). "Further studies are necessary to elucidate the association of SUMO4 polymorphisms with VKH syndrome in a HLA-DRw53 negative population using larger samples." (PMID 19122825, 2008).
cancer (4 papers, 2010 to 2022). A tumor composed of atypical neoplastic, often pleomorphic cells that invade other tissues. "For this reason, SUMO2, SUMO3 and SUMO4 can be potentially exploited in further anti-cancer mechanisms investigations (p-value = 0.024 in the present study), in order to shed light on the regulatory mechanisms underlying the activity of SUMO machinery in an oncogenic framework." (PMID 35741808, 2022). "In addition, we identified that the stress factors head trauma or cancer treated by radiochemotherapy, which are discussed as potential additional triggers of ALS pathogenesis via an increased generation of free radicals, occurred in carriers of the SUMO4 initiator codon variant prior to ALS onset." (PMID 35503374, 2022).
tumor (2 papers, 2022). "Although SUMO4 data are not included in these databases, our findings reveal strikingly different regulatory roles for SUMO1/2/3 in tumor immunity." (PMID 36589239, 2022).
renal diseases (1 paper, 2009). "In response to FFA, SUMO4 is capable of inducing the expression of inflammatory cytokines which target vessels and kidney in cardiovascular and renal diseases." (PMID 19997558, 2009).
SUMO4 also shares sentences with these, for which no sentence is quoted: autoimmune thyroid disease (2 papers); amyloidosis (1); Autoimmunity (1); breast carcinoma (1); colon adenocarcinoma (1); hepatitis C (1); juvenile idiopathic arthritis (1); lung adenocarcinoma (1); metabolic syndrome (1); neurodegenerative disease (1); ovarian serous cystadenocarcinoma (1); transient neonatal diabetes mellitus (1); uveitis (1).